LGSN (lengsin, lens protein with glutamine synthetase domain)
Description:
May act as a component of the cytoskeleton or as a chaperone for the reorganization of intermediate filament proteins during terminal differentiation in the lens. Does not seem to have enzymatic activity (By similarity).
Synonyms: GLULD1; LGS
Tractability: Antibody: its Gene Ontology location is reachable by antibodies, with medium confidence.
Gene: Protein-coding gene on chromosome 6 (63,275,951 to 63,319,983, reverse strand). Ensembl gene ENSG00000146166.
Subcellular location (Human Protein Atlas): Nucleoplasm; Vesicles
Gene Ontology:
Molecular function: glutamine synthetase activity; catalytic activity
Biological process: nitrogen utilization
Cellular component: cytoplasm; membrane; plasma membrane
Genetic constraint (gnomAD): Loss-of-function variants: 19 observed, 16.24 expected, observed/expected ratio (o/e) 1.17, 90% interval 0.81 to 1.69. The upper end of that interval is the gene's LOEUF score, 1.69, which puts it in group 6 of 6, group 1 being the genes least tolerant of losing a copy. Missense variants: 657 observed, 625.63 expected, observed/expected ratio (o/e) 1.05, 90% interval 0.98 to 1.12. Synonymous variants: 251 observed, 222.22 expected, observed/expected ratio (o/e) 1.13, 90% interval 1.02 to 1.25.
Homologues: Orthologues: chimpanzee LGSN (98% identical), macaque LGSN (94% identical), rabbit LGSN (86% identical), dog LGSN (85% identical), pig LGSN (84% identical), rat Lgsn (81% identical), mouse Lgsn (80% identical), guinea pig LGSN (79% identical), zebrafish lgsn (50% identical), tropical clawed frog LGSN (49% identical), Caenorhabditis elegans gln-5 (15% identical), Caenorhabditis elegans gln-6 (15% identical), and 2 more. Paralogues in human: GLUL (15% identical).
Diseases named in the same sentence as LGSN in open-access papers:
LGSN is named in the same sentence as 15 diseases in open-access papers, as found by Europe PMC text mining. Sharing a sentence is not in itself a finding about the gene and the disease. The quoted sentences say what the papers report.
Age-related cataract (1 paper, 2023). A type of cataract (opacification of the lens) that forms during the course of aging. "Although the dramatically decreased LGSN mRNA has a strong potential connection with age-related cataracts, the normal lens was completely immune-privileged and could be protected from the blood–organ barrier." (PMID 37612301, 2023).
autoimmune disease (1 paper, 2022). A disorder resulting from loss of function or tissue destruction of an organ or multiple organs, arising from humoral or cellular immune responses of the individual to their own tissue constituents. "We found that LGSN can also have a high expression in human tissues and may be associated with some human autoimmune diseases." (PMID 36292733, 2022).
breast carcinoma (1 paper, 2022). "LGSN, OCA2, and HERC2 reportedly mediated resistance to breast cancers." (PMID 36292733, 2022).
cataract (1 paper, 2024). Partial or complete opacity of the crystalline lens of one or both eyes that decreases visual acuity and eventually results in blindness. "Although LGSN has been previously identified as differentially expressed in lens tissues derived from rats with cataracts, its connection to glaucoma remains unclear." (PMID 38287276, 2024).
gastric cancer (1 paper, 2023). A primary or metastatic malignant neoplasm involving the stomach. "In particular, we determined the IC50 values of 5-FU, cisplatin, L-OHP, and Metformin (clinically approved drugs may induce pyroptosis in cancers) in LGSN-high and LGSN-low gastric cancer patients in TCGA database." (PMID 37612301, 2023).
gastric tumor (1 paper, 2023). "To further understand the interplay between LGSN and vimentin expression, we found that VIM expression was consistently and significantly up-regulated with LGSN expression in gastric tumor tissues from dataset GSE29272." (PMID 37612301, 2023).
lung carcinoma (1 paper, 2023). "However, other studies into cancer have identified LGSN as a tumor-associated antigen and revealed its essential role in lung carcinoma cell survival." (PMID 37612301, 2023). "LGSN is highly expressed in various types of cancers, including lung cancer." (PMID 37612301, 2023). "Previous study has indicated that targeting LGSN could present a novel therapeutic approach for treating lung cancer." (PMID 37612301, 2023). "Although LGSN splicing variant 4 has a reportedly high expression in lung cancer, no data have been gathered showing that LGSN is involved in the lung cancer stemness." (PMID 37612301, 2023). "Moreover, a previous study revealed that anti-LGSN immunological response in lung cancer patients is not harmful to the lens." (PMID 37612301, 2023).
lymph node metastasis (1 paper, 2023). "Immunohistochemical (IHC) staining of the TMA also revealed significantly different and relatively high LGSN expression in advanced T stage and TNM stage, poorly differentiated, and lymph node metastasis samples." (PMID 37612301, 2023).
myopia (1 paper, 2023). "Although the downstream targets of key myopia genes predicted by WGCNA and DEG analysis were not among the predicted targets of DZP, the molecular docking results showed that MIP and LGSN could firmly bind to the active constituents of DZP." (PMID 37747014, 2023).
cancer (1 paper, 2023). A tumor composed of atypical neoplastic, often pleomorphic cells that invade other tissues. "Therefore, we designed xenograft-tumor-bearing mouse therapeutic models to evaluate GCSC susceptibility to pharmaceutical intervention after LGSN-knockdown and the lessening of cancer severity in vivo." (PMID 37612301, 2023). "Depletion of LGSN combined with the chemo-drugs 5-fluorouracil and oxaliplatin could offer a unique and promising approach to synergistically rendering this deadly cancer eradicable in vivo." (PMID 37612301, 2023). "Given the crucial role of LGSN in regulating 5-FU and L-OHP resistance, we reasoned that genetically manipulating LGSN might push cancer cells toward the pyroptotic threshold, allowing cumulative lethal damage by chemotherapy and eventually the killing of cancers consisting of CSCs." (PMID 37612301, 2023). "We assessed LGSN protein expression on a tissue microarray (TMA) comprising 84 pairs of GC tissues and 8 GC samples without adjacent normal tissues and found a stepwise LGSN up-regulation in cancer tissue." (PMID 37612301, 2023).
tumor (1 paper, 2023). "Next, we confirmed in vivo that mice bearing LGSN-silenced GCSC cells had significantly slower tumor growth." (PMID 37612301, 2023). "Future experiments are needed to determine how the accompanying tumor microenvironment of GC responds to LGSN-mediated cell death evasion and to investigate more appropriate systematic therapeutic strategies." (PMID 37612301, 2023). "We further observed that LGSN expression was increased in an approximately linear manner, and tumor tissues had higher mRNA/DNA expression-based stemness indexes (mRNAsi/mDNAsi) than adjacent normal tissues from TCGA GC patients." (PMID 37612301, 2023). "Our results highlighted the importance of the tumor-initiation role of LGSN and the exact pyroptotic machinery affected in GCSCs and provided insights into the best chemoprevention strategies and most efficacious targeted therapeutic interventions." (PMID 37612301, 2023). "Moreover, the combination of repressed LGSN expression and chemo-drugs treatment dramatically inhibited tumor growth compared with the mild tumor suppression of the 5-FU and L-OHP treatments without LGSN suppression." (PMID 37612301, 2023). "Notably, genetic interference of LGSN effectively suppressed tumor formation by inhibiting GCSC stemness maintenance and provoking gasdermin-D-mediated pyroptosis through vimentin degradation/NLRP3 signaling." (PMID 37612301, 2023). "We found that LGSN-repressed xenografts were smaller in volume, and the 5-FU and L-OHP treatment groups showed mild tumor suppression." (PMID 37612301, 2023).
LGSN also shares sentences with these, for which no sentence is quoted: cholangiocarcinoma (1 paper); glaucoma (1); Hypoglycemia (1); ovarian carcinoma (1).